TNF (tumor necrosis factor)
Diseases named in the same sentence as TNF in open-access papers (continued):
Sharing a sentence is not in itself a finding about the gene and the disease.
breast carcinoma (continued). "Inflammatory markers such as TNF-α and IL-6 decreased after exercise training in a study of breast cancer survivors." (PMID 34638290, 2021). "Our current study findings have revealed that AWP1 plays a crucial role in the TNF-α-induced migration of breast cancer cells by showing that the ‘Nox1-ROS–NF-κB–EMT-related genes’ cascade can be potentially regulated by AWP1." (PMID 33816268, 2021). "The pro-inflammatory cytokines tumor necrosis factor α (TNFα) and interleukin 1β (IL-1β) are expressed simultaneously and have tumor-promoting roles in breast cancer." (PMID 33806906, 2021). "Altogether, our novel findings provide the evidence that TNF-α induces IP-10 expression in MCF-7 breast cancer cells via activation of the JNK/c-Jun signaling pathway." (PMID 34572567, 2021). "Overexpression of TGF-β, VEGF, and TNF-α have been detected in murine 4T1 metastatic model and breast cancer patients, leading to a reduction in the incidence of metastases and increasing the patient’s survival rate." (PMID 34572719, 2021). "TNF-α, an inflammatory cytokine that is strongly expressed in breast carcinomas, was reduced by 4-MTBITC." (PMID 34447314, 2021). "Studies have shown that the pathogenesis of breast cancer is closely related to a significant increase in the expression levels of inflammatory factors such as TNF-α and IL-6 in TNBC." (PMID 34838003, 2021). "In agreement with our results from MCF-7 breast carcinoma cells, IP-10 induction by TNF-α has been also reported in hepatocytes." (PMID 34572567, 2021). "We found that the Nox1 and Nox5 mRNA levels of AWP1 KO breast cancer cell lines were significantly higher than those of WT cells and these enhancement of Nox1 and 5 were further induced by TNF-α exposure." (PMID 33816268, 2021). "These evidence strongly suggest that TNF-α differentially regulates the mitochondrial subunits in luminal and basal breast cancer patients and determine the survival rate and span of the breast cancer patients." (PMID 33926547, 2021). "Activated human T cells are involved in the synthesis of IL-6, TNFα, and TGFβ which induce the expression of mesenchymal proteins such as fibronectin, vimentin, and Zeb1 in inflammatory breast cancer cells." (PMID 34220337, 2021). "A. canaliculatum extract (20 μg/mL) showed no significant cytotoxicity but attenuated the motility of MDA-MB-231 breast cancers exposed to tumor necrosis factor (TNF)-α." (PMID 34371964, 2021). "TNFα was also found to exert a large variety of metastasis-promoting activities, on breast cancer cells themselves and their surroundings." (PMID 34201054, 2021). "TNF-α is one of the essential pro-inflammatory cytokines of breast cancer patients found in the tumor microenvironment (TME), being secreted both by stromal cells (mainly tumor-associated macrophages) and the cancer cells themselves." (PMID 34490085, 2021). "The evidences here clearly suggest that TNF-α modulates metabolism differentially in ER/PR +ve and ER/PR −ve breast cancer cells by modulating the levels of critical assembly factors and subunits involved in mitochondrial respiratory chain supercomplexes." (PMID 33926547, 2021). "In this state, breast cancer cells secrete factors, such as parathyroid hormone related protein (PTHrP) or TNFα, that increase the secretion of soluble RANKL from osteoblasts." (PMID 33445695, 2021). "In view of these observations, in this study we determined the impact of continuous proinflammatory stimulation by both TNFα + IL-1β together on the malignancy phenotype of breast cancer cells." (PMID 34072893, 2021). "Neuropeptide substance P secreted by circulating breast cancer cells induces upregulation of TNFα and Ang2 in brain endothelial cells which increases their permeability and transmigration of tumor cells into the brain." (PMID 33671981, 2021).
breast carcinoma (continued). "A more specific study on the gene expression of biomarkers in breast cancer revealed that the expression levels of IL-6, TNF-α, and leptin were higher in the breast adipose tissues of women with high waist circumference." (PMID 35008370, 2021). "The staining of the inhibitory immune-receptor ligand programmed death-ligand 2 (PD-L2) and tumor necrosis factor-alpha (TNF-α) ligand OX40L in human breast cancer sections revealed T lymphocytes at the surface of CAF." (PMID 34094963, 2021). "In the present study, we demonstrated that TNFα specifically enhances tamoxifen efficacy via NCOR1 to suppress the growth of ERα-positive breast cancer." (PMID 34073371, 2021). "Simultaneously, blocking TNF-α in the tumor microenvironment significantly down-regulates NF-κB activity and reduces cancer cell proliferation and invasion in breast cancer." (PMID 33854604, 2021). "Concerning breast cancer, our group has extensively reviewed TNFα impact/role on the different subtypes." (PMID 33540543, 2021). "Long-term treatment of breast cancer cell line with a combination of TNFα and TGFβ induced epithelial-mesenchymal transition, mammosphere formation, and extreme overexpression of genes associated with stemness." (PMID 33957885, 2021). "To confirm the relevance of IFNα/TNFα-induced senescence induction in vivo, we blocked both cytokines in mice with 4T07-mCh breast cancer and analyzed the status of disseminated 4T07 cells in the lungs by immunofluorescence." (PMID 33536445, 2021). "Voluntary wheel activity is also able to decrease IL-6 and TNF-α circulation in a chemically induced breast cancer model." (PMID 35008220, 2021). "The findings indicate the involvement of polymorphisms of the IL-6, C-X-C motif chemokine ligand 8 (CXCL8), and TNF genes and modification of methylation in the TNF gene promoter favoring the occurrence of chronic breast pain after breast cancer surgery." (PMID 34685397, 2021). "For example, our recent study showed that TNFα selectively induces apoptosis in ERα-positive MCF7 breast cancer cells, suggesting that this protein can be potentially combined with tamoxifen in cancer chemotherapy." (PMID 34073371, 2021). "IL-6 and TNFα are both important molecules for this process, and the role of NFκB-dependent PD-L1 is under intensive research in breast cancer." (PMID 34299224, 2021). "Some studies have shown that U. lactuca polysaccharide can significantly reduce the serum levels of TNF-α and NO in breast cancer mice, indicating that UPE can regulate inflammatory response and reduce the level of inflammatory cytokines." (PMID 34677438, 2021). "Macrophages M1 cells generate interleukin (IL)-12 and tumor necrosis factor with antitumor effects in breast cancer cells." (PMID 34368166, 2021). "TNF-α can induce tumor proliferation and can increase the invasions of breast cancer cells through the modulation of several metastasis-related genes." (PMID 33517609, 2021). "In our recent work, we demonstrated that MMP9 is directly involved in TNF-α-induced breast cancer cell migration." (PMID 33572115, 2021). "Previous studies showed that TBC1D3 upregulated tumor necrosis factor-α (TNF-α)-induced breast cancer cell migration." (PMID 34553038, 2021). "While CTLA-4 is a protein related to the inflammatory response that is increased in breast cancer patients, contributing to immune downregulation, TNF-α is a pro-inflammatory cytokine that induces apoptosis promoted by the absence of leptin." (PMID 33644151, 2021). "In breast cancer, the proinflammatory and prometastatic cytokines TNFα and IL-1β are present in tumors together, from the time of malignant transformation and on, throughout the process of cancer progression." (PMID 34072893, 2021). "It has been revealed that TNFα/YAP/p65/HK2 signaling is able to mediate the migration of breast cancer cells." (PMID 34126594, 2021).
breast carcinoma (continued). "The increase of TNFα and additional cytokines have been previously reported in mammary tumors from MMTV-PyMT mice fed with a HFD." (PMID 34371939, 2021). "Previous studies have reported that PDCD6 promotes breast cancer growth and metastasis by regulating the cytoskeleton and mediating the proapoptotic activity of cisplatin and TNF-α through the downregulation of NF-κB expression in different biological process." (PMID 32746883, 2020). "Monocytes from breast cancer patients secreted lower levels of IL-1β, IL-6, and TNF, while monocytes from renal cell carcinoma patients showed elevated production of these cytokines along with IL-10, CCL3, IL-8, and VEGFα." (PMID 33042791, 2020). "Of these, the NF-κB signaling pathway is known to be sensitive to TNF signaling which plays a major role in immune activation, breast cancer invasion, and driving TLR and MAPK signaling involved in cell migration and tumor invasion." (PMID 33208156, 2020). "Studies have shown that high expression levels of IL-6 and TNF-α in breast cancer can lead to a decrease in survival and a significant increase in mortality, which is beneficial to the progression and dissemination of breast cancer." (PMID 32936241, 2020). "Mindful based stress reduction positively influences cytokine production (IL-6 and TNF-alpha) in breast cancer patients." (PMID 32434503, 2020). "TNFα has been proved to play a central role in initiation, promotion, and metastasis in most of cancers, in particular in breast cancer." (PMID 32391269, 2020). "For example, KSG-002, a new herb formula, was reported to inhibit breast cancer growth and metastasis by downregulating NF-κB-dependent TNFα secretion derived from TAMs." (PMID 32213179, 2020). "Our previous findings indicated vulnerability of the mitoxantrone-resistant breast cancer cells MCF-7/MX to cell death induced by TNF-α compared to the parent cells MCF-7." (PMID 32742605, 2020). "For example, TBC1D3 is observed to be overexpressed in breast cancer by promoting oxidized low-density lipoprotein receptor 1 expression required for cell migration involving in TNFα/NF-κB signaling." (PMID 33194704, 2020). "Recently, TNFα involves in the invasion and metastasis of breast cancer cells by promoting crosstalk between mitochondria and lysosomal function." (PMID 32986377, 2020). "TNF-α levels was significantly reduced in breast cancer patients that are chronically exposed to pesticides when compared to the unexposed ones (94.6 ± 8.52 pg/mL and 127.2 ± 13.99 pg/mL, respectively, p = 0.0443), while IL-1β was not different." (PMID 32984049, 2020). "For instance, studies have exhibited a dual role of TNF-α in treating breast cancer as a drug and a target." (PMID 32346605, 2020). "The cytokine profiles of canine malignant and metastatic mammary carcinomas were described, illustrating the upregulation of IL-1, IL-6, TNF-α, and IFN-α expression." (PMID 32225066, 2020). "This study was designed to investigate the anti-cancer effects of AIM on NF-κB-regulated proteins and cellular responses induced by TNF-α in breast cancer cells." (PMID 32455624, 2020). "TNF-α is involved in all stages of breast cancer progression, including cell proliferation, survival motility, and acquired resistance to chemotherapy." (PMID 32346605, 2020). "In conclusion, the present study demonstrates that chrysoeriol reduces TNFα-induced upregulation of CYP19 aromatase expression via inhibition of ERK MAPK-mediated EGR-1 expression in MCF-7 breast cancer cells." (PMID 33053908, 2020). "We identified a TNF-α-mediated epigenetic mechanism of apoptotic cell death regulation in estrogen receptor-α (ERα)-positive human breast cancer cells." (PMID 32455774, 2020). "Dysfunctional VAT secretes pro-inflammatory cytokines such as tumor necrosis factor-alpha (TNF-α) and interleukin-6 (IL-6), thereby stimulating aromatase activity, which eventually drives higher estrogen production to support luminal type breast cancer growth." (PMID 31992764, 2020).
breast carcinoma (continued). "Many studies have been conducted to understand the role of genetic polymorphism in cytokine genes including TNF-α and TNF-β in breast cancer patients." (PMID 32102503, 2020). "There has been quite a big controversy regarding TNFα expression as a parameter to predict clinical outcome in breast cancer patients." (PMID 32391269, 2020). "Specifically, the concentrations of IL6 and TNFα were higher in women with breast cancer with pooled mean difference of 2.15 (95% CI 1.64–2.66) and 1.70 (95% CI 1.10–2.30), respectively." (PMID 33004039, 2020). "We previously showed that overexpression of PKCε inhibited tumor necrosis factor-α (TNF)-induced apoptosis in breast cancer MCF-7 cells." (PMID 32549199, 2020). "TNF-α neutralizing antibodies are also tested for cooperation with paclitaxel, a conventional chemotherapeutic agent in breast cancer." (PMID 33123472, 2020). "KLF5 promotes migration and invasion by upregulating the transcription of TNFAIP2, a tumor necrosis factor-α (TNFα)-induced gene in breast cancer cells." (PMID 33424607, 2020). "The facts exposed here postulate TNFα as an attractive target potentially useful to treat different breast cancer subtypes." (PMID 32391269, 2020). "To our knowledge, we are the first group to report that TNFα increases MUC4 expression through activation of the NF-κB pathway in HER2-positive breast cancer." (PMID 32391269, 2020). "The secretome profile of MDA-MB-231 cells was similar to the expression of genes following treatment of breast cancer cells with TNF-α." (PMID 32883235, 2020). "Taking all this into account, TNFα-blocking agents are a promising tool to treat breast cancer patients in combination with current cancer therapies." (PMID 32391269, 2020). "Cytokine production is a central mechanism triggered by immune response against cancer, and high levels of systemic TNF-α and IL-1β has been reported in breast cancer patients." (PMID 32984049, 2020). "For example, breast cancer cells are shown to respond to higher circulating levels of certain pro-inflammatory cytokines, such as TNF-α, IL-1β, and IL-6 by increasing the expression of P450 aromatase." (PMID 32731638, 2020). "TNF-α was significantly increased in the breast cancer group (BC: 1.91 ± 0.39) compared to the normal mouse group (CTL: 1.00 ± 0.05, P < 0.03)." (PMID 32309219, 2020). "Third, sarcopenia is linked to proteolytic cascades, for instance the tumor necrosis factor (TNF-α), which have been demonstrated to promote tumor migration and invasion and are associated with a deterioration in breast cancer prognoses." (PMID 32131764, 2020). "In breast carcinomas, pro-inflammatory cytokines, such as tumor necrosis factor (TNF)-α, suppress laminin α3B (LAMA3B) but enhances LAMA4 expression." (PMID 33250894, 2020). "The proliferative effects of TNFα in human breast cancer cell lines in vitro were shown to be mediated by TNFR1, which activates JNK and PI3K/AKT which stimulates NF-κB." (PMID 32391269, 2020). "Increased production of TNF-α in MCF-7/ADR (Adriamycin) human breast cancer cell line due to transfection of these cells by TNF-α gene resulted in a significant reversal of resistance to ADR in this cell line." (PMID 32742605, 2020). "Our results confirm those of a previous report demonstrating elevated levels of TNF-α and IL-6 in sera of patients diagnosed with advanced breast cancer and high load of metastases." (PMID 32306920, 2020). "NFKB is highly active in the invasive breast cancer cells resulting in the secretion of a number of cytokines, a condition similar to that of cells treated with TNF-α." (PMID 32883235, 2020). "Natural isoflavones, such as genistein and daidzein, are known to inhibit TNFα-induced migration and invasion of human breast cancer cells by preventing the inhibition of NF-κB." (PMID 32708426, 2020). "Activation of NFkB by TNFα promotes breast cancer by promoting cell proliferation and migration in breast cancer cells." (PMID 32986377, 2020).
breast carcinoma (continued). "TNFα/type I IFN enhancement of apoptotic priming in breast cancer recipient cells highlights a synergistic pro-death activity between these two inflammatory cytokines, recently reported to induce necroptosis in RIPK3 competent (non cancer) cells." (PMID 31937780, 2020). "Considering the role of inflammation in cancers, the TNF-α--NF-κB axis has been shown to induce the malignant behavior and invasiveness of breast cancer." (PMID 32458652, 2020). "Recent findings indicated that TNF-α sensitized breast cancer cells against radiotherapy and chemotherapy." (PMID 32742605, 2020). "It is known that ERα cistrome is reprogrammable and TNFα has been shown to reshape the genomic action of estrogen in breast cancer cells through redistribution of NF-kB and pioneer factor FOXA1 binding across the genome." (PMID 32706336, 2020). "Accordingly, a previous study also reported elevated serum CTLA-4 levels in cats with mammary carcinoma, being associated with HER2-positive status and TNF-α levels, in accordance with our findings." (PMID 32481540, 2020). "In the present study, we have attempted to examine TNF-a 308G/A (rs1800629) and TNF-β +252 A/G (rs361525) gene polymorphism both at genotypic and allelic level and their association with breast cancer patients and healthy controls in Indian population." (PMID 32102503, 2020). "Our data demonstrated the presence of TNF-α-induced selective apoptotic cell death in ERα-positive MCF-7 human breast cancer cells; interestingly, this effect was dependent on caspase-7." (PMID 32455774, 2020). "It has been reported that TNFα treatment in certain breast cancer cell lines inhibits proliferation and induces apoptosis." (PMID 32391269, 2020). "PrPC levels were found to be higher in tumor necrosis factor α (TNF-α)-resistant breast cancer cells than in TNF-α-sensitive breast cancer cells." (PMID 33276687, 2020). "In mice, administration of TNF-α antibodies enhances the efficacy of paclitaxel treatment with respect to both breast cancer proliferation and lung metastasis." (PMID 33123472, 2020). "For example, TNF-α is an essential pro-inflammatory cytokine found in the TME of breast cancer patients." (PMID 32346605, 2020). "In particular, prolonged exposure to TNFα of breast cancer cell lines induces the upregulation of the transcriptional repressor Twist1 via activation of IKKβ and NF-κB and induces EMT and cancer stemness properties." (PMID 32391269, 2020). "Here, we show that the small molecule Akt antagonist MK-2206, when combined with the Th1 cytokines IFN-gamma and TNF-alpha, maximize indicators of apoptotic cell death in a panel of phenotypically-diverse human breast cancer lines." (PMID 32774769, 2020). "For example, STAT3 in TAMs from breast cancer is overactivated, which inhibits the expression of IL-12 and significantly promotes the secretion of TNF-α." (PMID 33005103, 2020). "We observed significantly reduced TNF-α levels in breast cancer patients that exhibited intratumoral clots and were exposed to pesticides." (PMID 32984049, 2020). "On the other hand, it has also been shown that most breast cancer cell lines are resistant to TNFα-induced apoptosis, and that their proliferation, survival, and progression are mediated by said cytokine." (PMID 32391269, 2020). "RANKL, a member of the tumor necrosis factor (TNF) family, plays a central role in the development of osteoclasts and breast cancer bone metastasis." (PMID 32226538, 2020). "We have previously reported that in HER2-positive breast cancer cell lines, TNFα transactivates HER2, inducing phosphorylation of Tyr877 through c-Src, in a PKC-dependent manner." (PMID 32391269, 2020). "Classical monocytes isolated from breast cancer patients also exhibit altered response to inflammatory stimuli, as indicated by their impaired secretion of TNFα and IL-1β in response to bacterial lipopolysaccharide." (PMID 33042791, 2020).